TNF (tumor necrosis factor)
Diseases named in the same sentence as TNF in open-access papers (continued):
Sharing a sentence is not in itself a finding about the gene and the disease.
tumor (continued). "In addition, the upregulation of PDL1 expression decreased the expression of proinflammatory cytokines (IFN‐γ, IL‐2, and TNF‐α) in mouse serum and tumor tissue samples and increased the expression of anti‐inflammatory cytokines (IL‐10)." (PMID 31557409, 2019). "Reduced ST2 might be related to the immunosuppressive milieu favored by the tumor microenvironment, since in vitro studies have shown that sST2 expression is induced by pro-inflammatory cytokines, such as IL1β and TNFα." (PMID 31281317, 2019). "Together, these findings point to a role for TNFα on IgE-mediated anti-tumour functions." (PMID 31544825, 2019). "TNF-α, another inflammatory cytokine, is responsible in the main pathways of tumor inflammation." (PMID 30642295, 2019). "Tumor cells showing BRAF V600E mutation tend to have increased cytokine secretion such as that of interleukin (IL)-1β, IL-6, and IL-8, because cytokines such as tumor necrosis factor alpha or IL-1β increase ATX and LPA levels." (PMID 31455351, 2019). "TNF-α-activated MSCs strikingly enhanced tumor metastasis compared with normal MSCs." (PMID 31130595, 2019). "Furthermore, TNFα also promotes tumor migration by inducing cytokines such as MMP-9 and chemokines receptors CCR9 and CCR5." (PMID 31398937, 2019). "Macrophages can be activated under a variety of stimuli to serve as killers toward tumor cells and specific pathogens via phagocytosis process or secretion of cytotoxic molecules including NO, interleukin-1 (IL-1), tumor necrosis factor-alpha (TNF-α) and reactive oxygen intermediates." (PMID 31661653, 2019). "Moreover, macrophages produce tumor necrosis factor α (TNF-α), which can indirectly increase tumor proliferation." (PMID 31185596, 2019). "One phase II trial assessed the use of injecting Mo-DCs loaded with tumour lysate and matured by TNFα, Poly I:C, and IFNγ in 15 patients with surgically amenable liver metastasis of colon adenocarcinoma that underwent neoadjuvant chemotherapy, surgery and adjuvant chemotherapy." (PMID 31091774, 2019). "Densitometric analysis of immunoblot experiments shows down-regulation of CSC biomarkers in all three CRC cells treated with either TNF-β or TNF-α and/or resveratrol, demonstrating that it is one of the multitargeting cellular and principle mechanisms of resveratrol for tumor suppression." (PMID 30917533, 2019). "We next examined the tumor-infiltrating capability of TNF-α-treated Th9 cells." (PMID 30717817, 2019). "NF-κB and AP-1 are major key players in TNF-α-mediated tumor progression." (PMID 31540489, 2019). "Additionally, NK cell cytokine production capacity (IFN-γ and TNF-α) and cytotoxic function against the gold standard NK cell tumor target K562 remained unaffected by mRNA transfection." (PMID 31231387, 2019). "NFκB regulates the expression of tumor necrosis factor alpha (TNFα) and interleukin-1β (IL-1β) in macrophages, whereas in tumor cells, increases the expression of anti-apoptotic molecules, contributing to increased resistance of cancer cell to current chemotherapies." (PMID 30995775, 2019). "CAFs are classified as tumor-restraining, tumor-promoting, secretory, or ECM-remodeling cells, which also exhibit CAF functions via mutated genes, the secreted cytokines IL-1β, TNF-α and NF-κB, inflammatory signals, epigenetic regulation, etc.." (PMID 31521169, 2019). "Moreover, this chimera system is able to increase the caspase activation and reduce the viability of tumor cells, in combination with Tumor Necrosis Factor(TNF)-related apoptosis-inducing ligand (TRAIL) therapy." (PMID 31861156, 2019). "However, Etanercept, a blocking mAb against TNFα, did not affect the tumoricidal activity of LF-IC primed monocytes, arguing for the presence of soluble factors other than TNFα responsible for the killing of the tumor cells in these experiments." (PMID 31600968, 2019).
tumor (continued). "Recent studies have found that the inflammatory factors TNF-α and IL-1β in the tumor microenvironment stimulate normal breast epithelial cells adjacent to the cancer to cause structural remodeling and EMT activation, leading to malignant transformation of normal tissues and recurrence of disease." (PMID 31514467, 2019). "Interestingly, we discovered that RHBDL2 expression is specifically induced in tumor cells by the inflammatory signal TNFα, which leads to E-cadherin cleavage and shedding." (PMID 31783481, 2019). "On the basis of the observed tumor promoting effects of TNFα, it was initially suggested that anti-TNFα antibodies might represent an effective anti-cancer therapy, and the ability of anti-TNFα antibodies to inhibit metastasis was demonstrated in late 1993." (PMID 30764482, 2019). "The study patients were treated with DCs stimulated by tumor lysate, TNF-α, and OK-432." (PMID 30693030, 2019). "They convert the tumor-inhibitory TNF into a tumor-promoting factor, and not only directly enhance the proliferation of some types of tumor cells, but also activate immunosuppressive cells and support immune escape and tumor development." (PMID 31921619, 2019). "Afterwards, the expression levels of 12 cytokines including IL-1a, IL-1b, IL-2, IL-4, IL-6, IL-8, IL-10, IL-12, IL-17A, TNFα, IFNγ and GM-CSF in secretome of hWJ-MSCs alone as well as in supernatant of tumor cells before and after treatment with hWJ-MSCs secretome were evaluated." (PMID 31857970, 2019). "TNF was originally identified as a direct contributor to tumor hemorrhagic necrosis." (PMID 30646912, 2019). "In addition, data from syngeneic immunocompetent tumor model also showed that VEGFR1-Fc treatment increased TNF-α/NF-κB1 pathway in refractory LLC tumors." (PMID 31829270, 2019). "This prompted us to quantify cytotoxic (granzyme B+) T cells in TNFα‐CSG‐treated 4T1 tumours." (PMID 31709774, 2019). "TNF-α and IFN-у appear to enhance eosinophilic production of pro-inflammatory Th1-type chemokines such as CXCL9 and CXCL10 whereas TNF-α and IL-4 stimulate eosinophilic production of Th2-type chemokines, which sustain a more immunosuppressive tumor microenvironment." (PMID 31730503, 2019). "Overall these results suggest that the reduced ROS expression combined to the high production of TNF could account for the anti-tumor activity of Sparc−/− myeloid cells." (PMID 31281314, 2019). "An inflammatory milieu of TNF-α treatment generally increased adhesion ability of the tumour cells." (PMID 31565662, 2019). "Finally, different studies have demonstrated the ability of TNFα to favor tumor escape from immune surveillance." (PMID 31659168, 2019). "Likewise, stress-induced immune alterations can enhance the generation and migration of many pro-inflammatory factors, such as interleukin (IL)-6, tumor necrosis factor (TNF-α) in the tumor microenvironment." (PMID 31737559, 2019). "In LLC and AB12 mesothelioma, TANs from the early tumors are more cytotoxic toward tumor cells and produce higher levels of TNF-α, NO, and H2O2, while these expressions are downregulated in late stages of tumors in which TANs acquire an enhanced pro-tumoral phenotype." (PMID 31474975, 2019). "In addition, the expression of inflammatory-related cytokines (IL-10 and TNF-α) in the tumours was significantly enhanced compared to control and vehicle groups." (PMID 31731436, 2019). "In addition, the RT-PCR analysis of tumor samples showed a decreased expression of TNF-α and IFN-gamma in the group exposed to BPA." (PMID 31137569, 2019). "Additional studies using high doses of TNF replicated TNF’s anti-tumor effects." (PMID 31174326, 2019). "During its initial production in the inflammatory response, TNF-α is also vital for maintaining chronic inflammation, angiogenesis, tissue remodeling, tumor growth, and metastasis; TNF-α blockers are therefore effective in treating a variety of acute and chronic inflammatory conditions." (PMID 31355282, 2019).
tumor (continued). "Interestingly, the reduction in ECM content in response to TNFα‐CSG treatment was positively correlated with immune cell infiltration in the RIP1‐Tag5 tumours, supporting the notion that the immune cell proteases degrade the ECM." (PMID 31709774, 2019). "However, there were no observable increases in the expression of the proinflammatory cytokines tested (IL-2, TNF-α, and IFNγ) within the tumor tissues." (PMID 30979375, 2019). "In a separate study, TNF was reported to activate the NF-κB signalling pathway and upregulate PD-L1 in human prostate and colon cancer cells, thereby promoting immunosuppression and favouring the tumour microenvironment." (PMID 30755793, 2019). "Furthermore, inflammation induces the accumulation of immune cells such as “antitumor” M1 macrophages (producing ROSs, IL-1β, TNFα, IL-6, and IL-12) in the tumor microenvironment, which are then reprogrammed by the tumor cells to a M2 phenotype." (PMID 31662751, 2019). "Moreover, Notch1 was up-regulated in the tumor cells at the mRNA and protein levels and was activated at the protein level in the tumor cells by TNFα stimulation." (PMID 31105691, 2019). "MAIT cells produced less IFN-γ and TNF-α in the presence of tumor-conditioned media." (PMID 31354725, 2019). "However, subsequent studies indicated that TNF-α is an important inflammatory factor in addition to its effects of killing tumor cells." (PMID 30646912, 2019). "A minor NK subset, within total circulating NK cells (5–10%), exhibits the CD56brightCD16− phenotype and is able to produce high and constant levels of anti-tumor cytokines, such as IFNγ and TNFα, CD56brightCD16− NK cells are abundant in healthy and neoplastic solid tissues." (PMID 31057536, 2019). "Moreover, the administration of a specific bacteria, Alistipes shahii, to antibiotic-treated tumor bearing mice, restores TNF production with a notable improvement in the therapeutic outcome." (PMID 30609850, 2019). "In mice with tumor, an increase in TNF-α plasma levels was also observed." (PMID 31540249, 2019). "Importantly, TNFα stimulation of TNBC:MSC “Contact” co-cultures in vitro has increased the aggressiveness of the tumor cells in vivo, leading to higher incidence of mice with lung metastases than non-stimulated TNBC:MSC co-cultures." (PMID 31031757, 2019). "Although shown to be polarized toward favorable proinflammatory M1 phenotype (with high levels of CD86, MHCII, and Ly6C), increased tumor necrosis factor alpha (TNFα) produced by these cells induced apoptosis in infected tumor cells and ultimately inhibited viral spread." (PMID 30764570, 2019). "Moreover, we identified that tumor cells communicate with astrocytes, where tumor cell-derived interleukin-1 beta (IL-1β) and tumor necrosis factor alpha (TNF-α) increased the expression of TGF-β2 in astrocytes." (PMID 31602400, 2019). "In addition, this study also revealed that the intrinsic apoptosis pathway (TNF-α/Bax/Caspase-3) activation was enhanced in the tumor tissues of mice in the IR + MEL group compared to the IR group." (PMID 31137873, 2019). "The level of TNF-α was significantly higher in tumor tissues than in normal tissues (p = 0.006)." (PMID 31382678, 2019). "Plasma IL-4, IL-6 and TNFα levels were significantly increased in tumor-bearing versus normal mice." (PMID 31752313, 2019). "Additionally, the tumor microenvironment promotes the tumor-associated type II macrophage differentiation, which will release high amounts of VEGF, PDGF, FGF-2, MMPs, TNF, and inducible nitric oxide synthase-released reactive oxygen species." (PMID 31905724, 2019). "Hence, the addition of blocking antibodies against the PD-1/PD-L1 axis or against TIM-3 effectively restored IFN-γ and TNF-α production by T cells in response to tumour antigens." (PMID 31358938, 2019).
tumor (continued). "Along this line, the intra-tumoral injection of CpG oligodeoxynucleotides administered together with an anti-interleukin-10 receptor (IL-10R) antibody, induce TNF production from tumor infiltrating myeloid cells and, in turn, reduce the growth several types of tumors in mice." (PMID 30609850, 2019). "IFN-γ and TNF-α have been shown to be central in viral and tumor clearance." (PMID 31426763, 2019). "Furthermore, IFN-γ and TNF-α, important cytokines for tumor surveillance and for inducing the activation of T cells and macrophages, are produced predominantly by NK cells and functionally linked to the cytotoxic activities of NK cells." (PMID 31097020, 2019). "In addition, a decrease in oxygen availability causes an increase in the expression of the cytokines IL-1ẞ, IL-6 and TNF-α, which in turn promotes tumor progression by stimulating VEGF expression." (PMID 31568519, 2019). "In addition, a plethora of factors that are abundant in infiltrated cells that infiltrate the tumor microenvironment (TANs in particular) such as IL-6, IL-8, IL-1β, and TNFα are also able to induce EMT in GC." (PMID 30616627, 2019). "iNOS and TNF-α were shown to mediate either tumor-promoting or antitumor effects and may therefore influence the efficacy of nRCT in cancer patients." (PMID 30984181, 2019). "Because various types of tumors produce several cytokines (IL-6, IL-8, TNFα) and growth factors (G-CSF), which are known to stimulate the activity of neutrophils, we aimed to investigate the influence of tumor-derived G-CSF on NET formation by the neutrophils isolated from the blood of HNC patients." (PMID 31438586, 2019). "Tumor necrosis factor-alpha (TNF-α) is an important cytokine that may trigger either death or tumor growth." (PMID 31137684, 2019). "PD-1/PD-L1 signaling plays a critical role in inactivating immune cells and maintaining plaque stabilization in atherosclerotic lesions although T cell activation and pro-inflammatory cytokines such as interferon-γ (IFN-γ) and TNF-α are highly appreciated in terms of anti-tumor effects." (PMID 31146442, 2019). "Similarly, tumor necrosis factor has exhibited direct antitumor property by killing some tumor cells and propagating the inhibition of tumor-induced vascularization." (PMID 31652460, 2019). "In contrast, other studies have shown Pgp upregulation mediated by TNF-α in tumor and normal cells." (PMID 31137684, 2019). "Activation of transcription factors induces NK cells expressing and secreting various cytokines, including FasL, tumor necrosis factor (TNF), and TNF-related apoptosis-inducing ligand, which kills tumor cells via the Fas/FasL pathway and the TNFα/TNF-receptor 1 (TNF-R1) pathway." (PMID 30813924, 2019). "However, of the biological anti-TNFα drug formulations, infliximab showed a stronger anti-tumor property than etanercept, especially in vivo." (PMID 30764482, 2019). "In addition, several cytokines, such as IL-4, IL-13, RANKL, and TNF-α, seem to play an important role in the process of macrophage fusion, myoblast fusion and even in tumour-hybrid formation." (PMID 31266502, 2019). "TNF-α is synthesized and secreted by malignant tumor cells and is abound in TME." (PMID 31380426, 2019). "This does not necessarily preclude effective Smac mimetic-based treatment of tumors composed of such cells though, as Smac mimetics can boost systemic TNFα levels, conceivably providing sufficient TNFα at the tumor site to enable Smac mimetics to activate cell death pathways." (PMID 31521127, 2019).
tumor (continued). "It is known that malignant epithelial cells secrete antiadipogenic cytokines, such as TNF-α, IL-11, and IL-6 that inhibit the differentiation of fibroblasts near the tumor into mature adipocytes and stimulate aromatase expression in these undifferentiated adipose fibroblasts." (PMID 31412584, 2019). "For example, co-expression of IL-2 and tumor necrosis factor (TNF-α), linked by IRES, in an oncolytic adenovirus genome, has allowed increases in the number of CD4+ and CD8+ tumor-infiltrating lymphocytes, as well as T-helper 1 (Th1) and CD86+ dendritic cells (DCs) in vivo." (PMID 31698727, 2019). "TNFα and IFNγ are often expressed in the tumors' microenvironment and these signals may be altered when tumor cells are passaged in culture." (PMID 30833945, 2019). "Also, in the context of TNFα stimulation, p65 activation that led to elevated Notch1 activation took place mainly in the tumor cells but also in the MSCs." (PMID 31105691, 2019). "In addition, TNF-α activates transcription factors and related genes and then stimulates the related cell signaling pathways, which promotes the proliferation of tumor cells." (PMID 31500658, 2019). "Moreover, these therapies can trigger a cytokine storm in the tumor stroma, such as the release of IL-6 and TNF-α, as well as activate macrophages to generate pro-inflammatory mediators to stimulate tumor growth and contribute to recurrence." (PMID 30999932, 2019). "Similarly, all but the FR-negative HOS-143b tumor cells triggered high levels of IFNγ, IL-2, and TNFα production after 44 h of co-culture at an E/T ratio of 1:1 with E2-CAR-T cells." (PMID 30941303, 2019). "Secondly, NLRP12 downregulates hepatocyte-specific expression of cytokines such as IL-6 and TNFα which promote proliferation and tumor growth, and chemokines CXCL1, CXCL2 and CCL2, which enhance inflammatory cell infiltration and thereby augment inflammation in the tumor milieu." (PMID 30990169, 2019). "P-KG03 sulphated polysaccharide, derived from marine microalgae Gyrodinium impudium strain KG03, activates the production of NO in a JNK-dependent manner and stimulates the production of cytokines IL-1β and 6 and TNF-α in macrophages, and prevents the growth of tumor cells in vitro and in vivo." (PMID 31083446, 2019). "TNF-α, granzyme B, and perforin were all downregulated in cells lacking JAK1; this was rescued by the re-expression of codon-optimized JAK1, implying that JAK1 deficiency prevents killing by tumor-specific T-cells." (PMID 30837996, 2019). "However, by intracellular FACS analysis we detected increases of TNFα and IFNγ expression in tumor infiltrating cells." (PMID 31214164, 2019). "Moreover, TNF-α is capable of inducing cell apoptosis, and in contrast, it can accelerate tumor growth." (PMID 30600678, 2019). "A bundle of evidences links TNF-α and NF-κB pathway to tumor survival, growth and invasion." (PMID 31340603, 2019). "Tumor necrosis factor (TNF) is characterized by its anti-tumor performance in cancer cells." (PMID 31810492, 2019). "The immune escape mechanism of tumors may also be involved in JNK-mediated tumor cell survival, such as interleukin and tumor necrosis factor." (PMID 31639019, 2019). "Gadolinium uptake rate doubled in the TNFα‐CSG‐treated tumours as compared with the CSG control." (PMID 31709774, 2019). "In the tumor environment, the increase of inflammatory cytokines (TNF-α, IL-6, and LPS) and ROS expression under oxidative stress is crucial for the induction of the NF-κB pathway, and NF-κB can also directly activate the expression of potent EMT inducers including Snail and ZEB factors." (PMID 31514467, 2019). "Additional evidence supporting TNF’s pro-tumor role came from studying TNF-KO mice." (PMID 31174326, 2019). "Moreover, the findings obtained with DAPT were recapitulated when Notch1 was knocked-down in the tumor cells by siRNA; in these experiments, Notch1 siRNA has led to similar reduction in TNFα-induced contact-dependent induction of CXCL8 as did DAPT." (PMID 31105691, 2019).